CD4 (CD4 molecule)
Diseases named in the same sentence as CD4 in open-access papers (continued):
Sharing a sentence is not in itself a finding about the gene and the disease.
HIV-1 infection (continued). "Loss of CD73+ CD4+ T cells may partly explain one of the most typical features of HIV-1 infection, namely reduced in vitro proliferative responses to typical CD4 recall antigens." (PMID 33477692, 2021). "We also explored whether AHI-associated DNA methylation changes in monocytes and CD4+ T lymphocytes at the earliest stages of acute HIV-1 infection were associated with clinically relevant outcomes following ART." (PMID 34388205, 2021). "More recently, Nef-induced exosome-associated ADAM17 was found to cause quiescent CD4+ T cells to become permissive to HIV-1 infection, whereas ADAM17 along with TNF-α could activate latent HIV-1 in primary CD4+ T lymphocytes and macrophages." (PMID 33567490, 2021). "Previous work had shown that initiation of ART during a 4 month time window after HIV-1 infection was associated with an enhanced likelihood of CD4+ T lymphocytes counts and CD4+ T lymphocytes being preserved with early therapy independent of seroconversion status." (PMID 34388205, 2021). "Additionally, CD4+ T cells from HIV-1 controllers with higher A3G expression levels are less susceptible to in vitro HIV-1 infection than are CD4+ T cells from HIV-1 controllers with lower A3G expression levels." (PMID 34211449, 2021). "The positive association of propionate level and CD4+/CD8+ ratio before HIV-1 infection could indicate propionate’s role in HIV-1 acquisition due to the high level of CD4+ T cells." (PMID 34879869, 2021). "Interestingly, a recent study demonstrated differential regulation of susceptibility to HIV-1 infection in CD4 T cells based on cell activation and metabolism." (PMID 34017335, 2021). "Importantly, memory CD4+ T cells are abundant in infant and fetal mucosa, thus providing a large pool of cells susceptible to HIV-1 infection and a long-lived HIV-1 cellular reservoir that reactivates upon cessation of cART17,19,39,40." (PMID 33637808, 2021). "Among CD4+ T cells, T helper 17 (Th17) cells are particularly susceptible to HIV-1 infection and are depleted from mucosal sites, which causes damage to the gut barrier, resulting in a microbial translocation-induced systemic inflammation, a hallmark of disease progression." (PMID 34819367, 2021). "There is an inherent hierarchy in the susceptibility of CD4 T cell subsets to HIV-1 infection." (PMID 32084246, 2020). "But type I IFNs might contribute to disease progression, if continuously activating more T cells and thus generating more targets during HIV-1 infection and thus driving progressive CD4+ T cell loss." (PMID 33224139, 2020). "However, the additional burden of HIV-1 infection resulted in less CD4+ T-cell infiltration, an increase in EBV-associated tumors and a trend towards an exhausted CD8+ T-cell phenotype." (PMID 32576602, 2020). "One study also revealed that Ad5-specific CD4+ T cells were much more susceptible to HIV-1 infection than CMV-specific CD4+ T cells, and it might be related to the upregulated α4β7 integrin expression on CD4+ T cells." (PMID 32911701, 2020). "Whether upregulation of these multifunctional proteins directly contributes to reduce the susceptibility of CD4+ T cells and/or macrophages to HIV-1 infection in vivo, however, has been more difficult to prove." (PMID 32615986, 2020). "The result could be heightened activation, which for HIV-1 infection, could mean greater susceptibility of target CD4 T cells." (PMID 33253162, 2020). "Activated iNKT cells were more susceptible to HIV-1 infection than conventional CD4 T cells." (PMID 31190065, 2020). "Notably, Caspase-1 and IL-1β are associated with pryoptosis, or inflammation mediated apoptosis; pryoptosis is linked to progression of HIV-1 infection via CD4+ T-cell depletion." (PMID 32117283, 2020).
HIV-1 infection (continued). "For example, ALVAC-specific CD4+ T cells from RV144 vaccinees that show protection against HIV-1 infection display a polarized Th1-like phenotype shown to be less susceptible to HIV-1 infection, which could positively influence the efficacy of the RV144 trial." (PMID 32041218, 2020). "Notably, it has been reported that the levels of immune activation early in HIV-1 infection are positively associated with viremia and determine the rate of CD4+ T cell loss in untreated individuals." (PMID 32075764, 2020). "This assay shows that CD4+ T cells from the individuals were susceptible to HIV-1 infection." (PMID 32024974, 2020). "The α4β7 integrin may cause CD4+ T cells to migrate into the gastrointestinal tissue, where CD4+ T cells are mainly depleted during acute HIV-1 infection." (PMID 32911701, 2020). "Thus, this measure of microbial translocation early during HIV-1 infection is directly associated with the kinetics of longitudinal CD4+ T cell decline." (PMID 31449552, 2019). "Understanding viral factors associated with the VNP phenotype in HIV-1 infection may help to unveil cytopathic mechanisms of CD4+ T cell depletion in vivo." (PMID 30944395, 2019). "This could contribute to the pyroptosis-induced CD4 T cell loss characteristic during HIV-1 infection." (PMID 30867315, 2019). "In addition, studies have reported that human immunodeficiency virus type 1 (HIV-1) infection causes a large reduction in CD4+ T cells, precisely because HIV-1 infection induces pyroptosis." (PMID 31744077, 2019). "Since macaques (predominantly rhesus macaques) serve as the current animal model for HIV-1, we sought to determine whether some allelic variants of rhesus macaque CD4 might encode receptors that better support HIV-1 infection." (PMID 31181085, 2019). "Among the hallmarks of HIV-1 infection is the resulting longitudinal loss of CD4 T cells." (PMID 30867315, 2019). "Thus, VitD exhibited an in vitro protective role against HIV-1 infection, decreasing the susceptibility of CD4+ T, regardless the viral strain." (PMID 31550271, 2019). "In previous studies, some CSFV-infected peripheral lymphoid organs also showed positive TUNEL staining for cells that were not infected with CSFV, which likely occurred due to identical mechanisms through which HIV-1 infection causes bystander CD4+ T-cell death." (PMID 31744077, 2019). "Likewise, we observed preexposure of resting CD4+ T cells to CECs significantly enhanced their susceptibility to HIV-1 infection." (PMID 31772057, 2019). "Maraviroc has been reported to increase CCR5 expression on CD4+ T cells in both humans and macaques, suggesting that it could actually increase the susceptibility of T cells to HIV-1 infection." (PMID 31304185, 2019). "While translocation of microbial products, such as LPS, has been linked to immune activation and disease progression during chronic HIV-1 infection, we sought to specifically establish a link between very early microbial translocation and subsequent CD4+ T cell loss." (PMID 31449552, 2019). "To further investigate this hypothesis, we used our simulated data on CD4+ T cell densities and epithelial tissue damage to calculate the overall risk of HIV-1 infection when the entire female genital tract is exposed to HIV-1 in semen." (PMID 29698393, 2018). "We found that the stimulation of resting CD4+ T cells with either PHA-P or the anti-CD3/CD28 antibodies could significantly diminish SUN2 expression, which helps to explain the increased susceptibility of activated primary CD4+ T cells for HIV-1 infection." (PMID 29717016, 2018). "CD81 associates with CD4 and is critical for HIV-1 infection." (PMID 29429034, 2018). "Further analysis revealed that one of these miRNAs, miR-21, was down-regulated in monocytes during HIV-1 infection and responsible for the increase in IP-10 levels leading to inflammation and the rapid loss of CD4+ T cells, which is closely related to disease progression." (PMID 30619232, 2018).
HIV-1 infection (continued). "To gain further insight into the causes underlying the induction of HIF-1α during HIV-1 infection of CD4+ T cells, we evaluated the hypothesis that by inducing mtROS, HIV-1 triggers HIF-1α activity." (PMID 30206166, 2018). "With a particular focus on the newly developed HSV-2 antiviral drug pritelivir, we showed that certain doses may decrease the risk factors linked with HIV-1 infection susceptibility, namely CD4+ T cell count and HSV-2 lesion severity." (PMID 29698393, 2018). "Moreover, CCL11 has also previously been associated with more rapid CD4 loss below 350 cells/μl during acute HIV-1 infection." (PMID 29967620, 2018). "Lack of disease in SMs and AGMs has been ascribed to limited infection and/or loss of specific CD4+ T cell types that are prominent targets in HIV-1 infection, such as central memory (Tcm) and stem-cell memory (Tscm) subsets, Th17 cells, and T follicular helper (Tfh) cells in lymphoid tissue." (PMID 29659623, 2018). "This caused the generation of an inflammatory microenvironment which predisposed unactivated CD4+ T-cells to HIV-1 infection, which might contribute to viral spreading and reservoir seeding." (PMID 29997630, 2018). "Indeed, increased ROS production during HIV-1 infection has been associated with CD4+ T cell apoptosis." (PMID 30206166, 2018). "Notably, this IFITM variant is especially abundant in primary human cells (CD4+ T cells and monocytes) that serve as targets for HIV-1 infection in vivo." (PMID 29162141, 2017). "Hence, we decided to specifically analyze cell cycle-associated gene modulations during HIV-1 infection in CD4+ T cells to identify novel host-pathogen interactions in this context." (PMID 28184007, 2017). "Profound loss of CD4+ T cells, progressive impairment of the immune system, inflammation, and sustained immune activation are the characteristics of human immunodeficiency virus-1 (HIV-1) infection." (PMID 28839349, 2017). "Finally, we sought to demonstrate the hallmark decline in circulating CD4+ T-cells over time, which has been shown to follow HIV-1 infection in humans, NHPs, and other Hu-mouse models." (PMID 29127409, 2017). "Moreover, early HIV-1 infection causes extensive depletion of CD4+ T cells in the gastrointestinal tract that herald persistent inflammation due to the translocation of enteric microbes to the systemic circulation." (PMID 28241075, 2017). "Thus, miR-221/miR-222 act as modulators of CD4 mRNA expression throughout the myeloid cell lineage in differentiation-activation processes, in addition to modulating macrophage susceptibility to HIV-1 infection." (PMID 29301198, 2017). "This indicates that the extent of CD2low CD4+ T cell infection might be linked to the course of HIV-1 infection and viral loads in patients." (PMID 28953327, 2017). "Importantly, CD4 CTL emerge early during HIV-1 infection, correlate with acute viral load, and are associated with early viral load set point." (PMID 28167943, 2017). "Chronic inflammation in HIV-1 infection is linked to acute inflammatory events in the gut-associated lymphoid tissue (GALT) initiated by massive HIV-1 infection and death of CD4+ T cells that predispose this tissue to translocation of microbial products from the lumen." (PMID 29312342, 2017). "DCs are susceptible to HIV-1 infection although less permissive compared to activated CD4+ T cells." (PMID 27505169, 2016). "The immune hyperactivation associated with HIV-1 infection may lead to erosion, depletion and exhaustion of the CD4+ T-cell pool compromising the specific immune responses against HIV-1." (PMID 26785250, 2016). "It has been reported that reduced glycosylation of Env may enhance binding to α4β7 integrin found on gut CD4+ T cells, which may then be associated with rapid depletion of this Th17 T cells in the gut during early HIV-1 infection." (PMID 27906032, 2016). "Therefore, SAMHD1 in SAMHD1+ CD4+ T cells became susceptible to SIV-Vpx mediated degradation during chronic HIV-1 infection." (PMID 27922067, 2016).
HIV-1 infection (continued). "During chronic progressive HIV-1 infection, there is also progressive loss of CD4+ lymphocytes and perturbation of immune function, which may be due to the dysregulation of IL-2 and other cytokines through unrevealed pathways." (PMID 27145859, 2016). "Our findings support a model where progressive loss of central memory CD4 T cells in chronic HIV-1 infection is driven by increased cell cycle entry followed by mitotic arrest, leading to a non-apoptotic death pathway without actual proliferation, possibly contributing to increased turnover." (PMID 27875993, 2016). "Overall, these differences in viral tropism may explain the differential contribution of the TN CD4+ T-cell subset to the total pool of infected cells in each subject, as their susceptibility to HIV-1 infection is highly dependent on CXCR4 co-receptor usage." (PMID 27484989, 2016). "To further examine the impact of donor age on the susceptibility of CD4+ T cells to HIV-1 infection and replication, we used X4 and R5 HIV-1 NL4-3 reporter viruses co-expressing the enhanced version of the green fluorescent protein (eGFP) and Nef via an internal ribosome entry site (IRES)." (PMID 26452480, 2015). "Moreover, by increasing Glut-1 expression, quiescent CD4+ T cells become more susceptible to HIV-1 infection and down-regulation of Glut-1 abrogates the infection." (PMID 25875202, 2015). "The progressive loss of CD4+ T cell population is the hallmark of HIV-1 infection but the mechanism underlying the slow T cell decline remains unclear." (PMID 26709961, 2015). "The overall pathogenesis of HIV-1 infection is triggered by the destruction or depletion of CD4+ T-lymphocytes which consequently lead to the loss of immune competence and an increase in the susceptibility of the infected individuals to other infectious diseases." (PMID 25948238, 2015). "During acute HIV-1 infection, a massive loss of memory CD4+ T cells occurs throughout the body." (PMID 24671203, 2014). "However, LP CD4+ T cells are more susceptible to HIV-1 infection than resting HLAC CD4+ T cells due to higher activation levels and expression of HIV-1 co-receptors." (PMID 24495380, 2014). "Finally, we found that the expression of NefF12 in exosome-producing cells was sufficient to induce the susceptibility to HIV-1 infection in unstimulated CD4+ T lymphocytes." (PMID 24924541, 2014). "Counteracting inflammation and immune activation in HIV-1 infection may require resolving critical knowledge gaps about how HIV-1 causes extensive LP CD4+ T cell death during primary infection." (PMID 24495380, 2014). "In summary, these observations were consistent with the hypothesis that CD4+ T cells could have played a role in vaccine-associated risk of HIV-1 infection in Step." (PMID 25369172, 2014). "Overall, then HIV-1 infection is associated in general with a modest increase in Tregs relative to the conventional CD4 T cells that they normally regulate, and, if anything, may be more active than normal." (PMID 25610441, 2014). "Increased CTLA- 4 expression correlates with markers of HIV disease progression and the up-regulation of the CTLA- 4 also increases CCR5 expression on the surfaces of CD4+ T-lymphocytes which enhance the susceptibility of these cells to HIV-1 infections and cell to cell HIV transmission." (PMID 23849678, 2013). "The hallmark of HIV-1 infection is a progressive reduction of CD4 T cells." (PMID 23382678, 2013). "Human blood monocytes and resting CD4+ T-cells from SAMHD1-deficient AGS patients are more susceptible to in vitro HIV-1 infection compared with normal cells, suggesting that hSAMHD1 contributes to HIV-1 restriction in non-cycling immune cells through an intrinsic mechanism." (PMID 24257155, 2013). "The reduction of HLA-G+ CD4 Treg during progressive HIV-1 infection may be related to their increased susceptibility to HIV-1 infection, which is likely due to enhanced expression of the viral co-receptors CCR5 and CXCR4 demonstrated in this study." (PMID 23382678, 2013).
HIV-1 infection (continued). "Moreover, we show that phenotypic differences in the cortical actin in naïve and memory CD4+ T cells subsets determine the degree of viral antigen transfer inducing distinct susceptibilities to HIV-1 infection." (PMID 24244453, 2013). "Apart from their intrinsic susceptibility, CD4 + T cells’ activation in vivo (during the natural courses of HIV-1 infection) and in vitro (typically with PHA/IL-2 stimulation) is generally recognized as an absolute prerequisite for the virus to replicate productively." (PMID 23635305, 2013). "Our results indicate a profound reduction of HLA-G+ CD4 Treg in individuals with progressive HIV-1 disease that may stem from a higher susceptibility of these cells to HIV-1 infection, and functionally contribute to HIV-1-associated immune overactivation." (PMID 23382678, 2013). "However, the causes for the inherent resistance of naïve CD4+ T cells to HIV-1 infection cannot be explained by the different expression of viral coreceptors or the degree of activation of cells." (PMID 24244453, 2013). "However, TNF-α has been linked to the immune activation and the enhancement of HIV-1 infection in CD4+ T cells." (PMID 24156302, 2013). "Furthermore, antigen-specific recognition would increase T-cell activation and, as a result, the susceptibility of CD4+ T cells to productive HIV-1 infection." (PMID 23590845, 2013). "In order to investigate the protective or pathogenic roles of Type I IFN in an animal model of HIV-1 infection, we examined the relationship between plasma levels of IFNα, viral loads and peripheral CD4+ T cell counts during acute and chronic SIV infection in rhesus macaques." (PMID 24130482, 2013). "Indeed, the activated CD4+ T cells are highly susceptible to HIV-1-infection and die quickly as a result of cytopathic effects either of the virus or of the host immune system." (PMID 22548060, 2012). "Furthermore, mDCs efficiently interact with CD4+ T cells in lymphoid tissues; key sites of viral replication, where naïve CD4+ T cells are activated and turn highly susceptible to HIV-1 infection." (PMID 22545022, 2012). "Finally, expression of the C-terminal domain of Nup62 in CD4+ T cells reduced the association of IN with chromatin and did inhibit HIV-1 infection." (PMID 22928108, 2012). "CD4+ T-cells from gut-associated lymphoid tissues (GALT) are major targets for HIV-1 infection." (PMID 22470433, 2012). "In the current study we compared the role of the HIV-1 accessory protein, Vpr, during single-cycle and replication-competent HIV-1 infection of PBMCs, CD4+ T-cells and MDDCs, cell types that are distinct with respect to their cell cycle status and susceptibility to HIV-1 infection." (PMID 22570689, 2012). "Although activated CD4+ T cells are generally considered to be prime targets for HIV-1 infection and replication, cellular susceptibility to HIV-1 infection requires the expression of either the CCR5 (in early infection) or CXCR4 (in late infection) co-receptor." (PMID 22214232, 2012). "HIV-1 infection is associated with a progressive loss of CD4+ T cells and immune hyperactivation." (PMID 23285102, 2012). "Moreover, further insight into the early events during HIV-1 infection can help to better understand the mechanisms leading to systemic T cell activation and progressive loss of blood CD4+ T cells." (PMID 23056251, 2012). "Although HIV-1 infection of naïve CD4+ T-cells occurs at low frequency in comparison to that of activated effector/memory CD4+ T-cells, HIV-1 infection is associated with quantitative and qualitative changes within the naïve CD4+ T-cell compartment in both children and adults." (PMID 21298072, 2011). "In addition to viral detection, we also looked for any evidence of helper CD4 T cell loss which is a typical feature of HIV-1 infection." (PMID 21673796, 2011).